RTN4RL2 (reticulon 4 receptor like 2)
Description:
Cell surface receptor that plays a functionally redundant role in the inhibition of neurite outgrowth mediated by MAG (By similarity). Plays a functionally redundant role in postnatal brain development. Contributes to normal axon migration across the brain midline and normal formation of the corpus callosum. Does not seem to play a significant role in regulating axon regeneration in the adult central nervous system. Protects motoneurons against apoptosis; protection against apoptosis is probably mediated by MAG (By similarity). Like other family members, plays a role in restricting the number dendritic spines and the number of synapses that are formed during brain development. Signaling mediates activation of Rho and downstream reorganization of the actin cytoskeleton.
Synonyms: NgR2; NGRH1
Tractability: Antibody: UniProt places it where antibodies can reach, with high confidence; its Gene Ontology location is reachable by antibodies, with high confidence; UniProt predicts a signal peptide or a membrane-spanning region. PROTAC: its protein half-life has been measured.
Gene: Protein-coding gene on chromosome 11 (57,460,528 to 57,477,534, forward strand). Ensembl gene ENSG00000186907.
Subcellular location: Cell membrane; Membrane raft; Cell projection, dendrite; Perikaryon; Cell projection, axon
Pathways (Reactome):
Metabolism of proteins: Post-translational modification: synthesis of GPI-anchored proteins
Gene Ontology:
Molecular function: signaling receptor activity
Biological process: axon regeneration; cell surface receptor signaling pathway; negative regulation of neuron projection development; positive regulation of synapse assembly; corpus callosum development
Cellular component: cell surface; extracellular exosome; membrane raft; plasma membrane; axon; external side of plasma membrane; extracellular region; neuron projection; perikaryon; dendrite
Genetic constraint (gnomAD): Loss-of-function variants: 9 observed, 20.8 expected, observed/expected ratio (o/e) 0.43, 90% interval 0.26 to 0.75. The upper end of that interval is the gene's LOEUF score, 0.75, which puts it in group 3 of 6, group 1 being the genes least tolerant of losing a copy. Missense variants: 421 observed, 478.89 expected, observed/expected ratio (o/e) 0.88, 90% interval 0.81 to 0.95. Synonymous variants: 279 observed, 241.3 expected, observed/expected ratio (o/e) 1.16, 90% interval 1.05 to 1.28.
Homologues: Orthologues: chimpanzee RTN4RL2 (99% identical), macaque RTN4RL2 (98% identical), dog RTN4RL2 (97% identical), pig RTN4RL2 (97% identical), rat Rtn4rl2 (95% identical), mouse Rtn4rl2 (95% identical), guinea pig RTN4RL2 (72% identical), zebrafish rtn4rl2a (49% identical), zebrafish rtn4rl2b (48% identical). Paralogues in human: RTN4RL1 (46% identical), RTN4R (40% identical), NYX (27% identical), LRRC15 (25% identical), FLRT2 (25% identical), LRRC4B (24% identical), FLRT1 (24% identical), FLRT3 (24% identical), LRRTM4 (24% identical), LRRC4 (23% identical), LRRTM3 (23% identical), LRRC4C (23% identical), and 10 more.
Diseases named in the same sentence as RTN4RL2 in open-access papers:
RTN4RL2 is named in the same sentence as 10 diseases in open-access papers, as found by Europe PMC text mining. Sharing a sentence is not in itself a finding about the gene and the disease. The quoted sentences say what the papers report.
pneumonia (1 paper, 2019). An acute, acute and chronic, or chronic inflammation focally or diffusely affecting the lung parenchyma, caused by an infection in one or both of the lungs (by bacteria, viruses, fungi, or mycoplasma.). "Moreover, the expression of eight DEPs (PECAM1, PGLYRP1, AHCY, BHMT, EML3, ICOSLG, IGHV3‐23 and RTN4RL2) in normal and pneumonia groups (two patients) was quite different from that in the KD group." (PMID 30761252, 2019). "Moreover, the expression of eight of these 30 DEPs (PECAM1, PGLYRP1, AHCY, BHMT, EML3, ICOSLG, IGHV3‐23 and RTN4RL2) clustered normal and pneumonia samples into one group and clustered KD samples into another group, which heightens the importance of these eight DEPs in KD." (PMID 30761252, 2019).
cancer (1 paper, 2022). A tumor composed of atypical neoplastic, often pleomorphic cells that invade other tissues. "To further investigate the role of NgR2 during cancer progression and in cell motility, we reduced NgR2 expression in NCI-H660 cells and C4-2B cells that exogenously express αVβ3 using a pool of siRNAs against RTN4RL2 (NgR2)." (PMID 36344556, 2022).
RTN4RL2 also shares sentences with these, for which no sentence is quoted: tumor (3 papers); Anxiety (1); cognitive decline (1); depression (1); E. coli infection (1); neurodegenerative disease (1); prostate carcinoma (1); prostate tumors (1).